OTUD6B (OTU deubiquitinase 6B)
Description:
[Isoform 1]: Deubiquitinating enzyme that may play a role in the ubiquitin-dependent regulation of protein synthesis, downstream of mTORC1. May associate with the protein synthesis initiation complex and modify its ubiquitination to repress translation. May also repress DNA synthesis and modify different cellular targets thereby regulating cell growth and proliferation. May also play a role in proteasome assembly and function. [Isoform 2]: Stimulates protein synthesis. Influences the expression of CCND1/cyclin D1 by promoting its translation and regulates MYC/c-Myc protein stability.
Synonyms: DUBA5; CGI-77; DUBA-5; IDDFSDA
Tractability: PROTAC: ubiquitination databases record sites on it; its protein half-life has been measured.
Target class: Enzyme; Hydrolase
Gene: Protein-coding gene on chromosome 8 (91,070,196 to 91,087,095, forward strand). Ensembl gene ENSG00000155100.
Subcellular location (Human Protein Atlas): Cytosol; Golgi apparatus; Nucleoplasm
Gene Ontology:
Molecular function: cysteine-type deubiquitinase activity; protein binding
Biological process: cell population proliferation; proteasome assembly; protein deubiquitination
Cellular component: eukaryotic translation initiation factor 4F complex
Genetic constraint (gnomAD): Loss-of-function variants: 17 observed, 17.23 expected, observed/expected ratio (o/e) 0.99, 90% interval 0.67 to 1.48. The upper end of that interval is the gene's LOEUF score, 1.48, which puts it in group 6 of 6, group 1 being the genes least tolerant of losing a copy. Missense variants: 206 observed, 195.92 expected, observed/expected ratio (o/e) 1.05, 90% interval 0.94 to 1.18. Synonymous variants: 68 observed, 69.52 expected, observed/expected ratio (o/e) 0.98, 90% interval 0.8 to 1.2.
Gene-disease validity (ClinGen):
ClinGen rates the evidence that OTUD6B causes each of these diseases.
syndromic intellectual disability (autosomal recessive): Definitive. A intellectual disability that is part of a larger syndrome.
Homologues: Orthologues: chimpanzee OTUD6B (99% identical), guinea pig OTUD6B (93% identical), rabbit OTUD6B (92% identical), pig OTUD6B (91% identical), dog OTUD6B (90% identical), mouse Otud6b (89% identical), rat Otud6b (85% identical), macaque OTUD6B (76% identical), zebrafish otud6b (62% identical), tropical clawed frog otud6b (57% identical), Drosophila melanogaster CG7857 (40% identical), Caenorhabditis elegans otub-3 (33% identical), and 2 more. Paralogues in human: OTUD6A (54% identical), OTUD1 (19% identical), OTUD3 (18% identical), OTUD5 (17% identical), OTUD4 (12% identical).
Diseases named in the same sentence as OTUD6B in open-access papers:
OTUD6B is named in the same sentence as 54 diseases in open-access papers, as found by Europe PMC text mining. Sharing a sentence is not in itself a finding about the gene and the disease. The quoted sentences say what the papers report.
hepatocellular carcinoma (9 papers, 2020 to 2025). A malignant tumor that arises from hepatocytes. "The deubiquitinase OTUD6B inhibits cell migration in clear cell renal cell carcinoma and hepatocellular carcinoma by stabilizing mutated pVHL." (PMID 38880876, 2024). "But OTUD6B inhibited hepatocellular carcinoma metastasis and suppressed cell migration in clear cell renal cell carcinoma." (PMID 40651961, 2025). "OTUD6B has been displayed to predict better patient survival in clear cell renal cell carcinoma and hepatocellular carcinoma through decreasing the ubiquitylation and proteasomal degradation of pVHL." (PMID 36052059, 2022). "While in Hepatocellular carcinoma (HCC), OTUD6B decreases HIF-1α accumulation in HCC cells under hypoxia via directly interacting with pVHL to reduce its ubiquitination and proteasomal degradation, thereby inhibiting HCC cell metastasis." (PMID 37752518, 2023). "We found that deubiquitylase ovarian tumor domain-containing 6B (OTUD6B) induced the inactivation of HIF pathway by enhancing the stability of pVHL, and suppressed hepatocellular carcinoma (HCC) metastasis." (PMID 35110537, 2022). "OTUD6B suppressed hepatocellular carcinoma metastasis, involving a feedback loop consisting of OTUD6B, pVHL, and HIF-1α; CircPTPN12 bolstered the assembly of the PDLIM2/OTUD6B complex and inhibited hepatocellular carcinoma progression by PDLIM2/NF-κB pathway." (PMID 40651961, 2025).
breast cancer (8 papers, 2014 to 2025). A primary or metastatic malignant neoplasm involving the breast. "In conclusion, our work identifies OTUD6B as a breast cancer-associated deubiquitinase that stabilises KIFC1 during mitosis, to support pseudo-bipolar spindle formation and cell survival." (PMID 39789388, 2025). "The top DUB candidate to emerge from these screens was OTUD6B, which is amplified and associated with poor prognosis in breast cancer." (PMID 39789388, 2025). "We found that OTUD6B is frequently amplified or overexpressed leading to elevated protein levels in the TCGA breast cancer cohort, where it is associated with worse survival (Fig. EV1E) and basal-like TNBC (Fig. EV1G), and positively correlates with KIFC1 protein levels (Fig. EV1H)." (PMID 39789388, 2025). "OTUD6B is commonly overexpressed in breast cancer, correlating with KIFC1 protein expression and worse patient survival." (PMID 39789388, 2025). "Of our two candidates, we prioritised OTUD6B for mechanistic investigation, as it is frequently altered in clinical breast cancer and correlates with KIFC1 protein levels (Fig. EV1)." (PMID 39789388, 2025). "Together these data suggest OTUD6B is a legitimate protein target that is overexpressed in breast cancer." (PMID 39789388, 2025). "Mao’s study identified six autoantibodies, including OTUD6B, were present in mice prior to the development of mammary cancer through spontaneous mammary tumor models in transgenic mice (TgMMTV-neu)." (PMID 40651961, 2025). "We identified 6 autoantibodies that were present in mice prior to the development of mammary cancer: Pdhx, Otud6b, Stk39, Zpf238, Lgals8, and Vps35." (PMID 24886063, 2014). "Furthermore, in mouse mammary tumors, vaccination with tumor antigens (Otud6b, Pdhx or Stk39) induced tumor-specific CD4+ and CD8+ T cells, along with tumor-specific IFN-g T cell and CD8+ T cell responses." (PMID 40651961, 2025). "Notably, OTUD6B is amplified and overexpressed in breast cancer, and we show is required for survival of TNBC cell lines with either high (BT549) or moderate (MDA-MB-231) levels of amplified centrosomes." (PMID 39789388, 2025). "It suggested that antigen (including OTUD6B) expressed earlier in breast tumor development might be effective targets for therapeutic breast cancer vaccines." (PMID 40651961, 2025). "In addition, recent studies have shown that OTUD6B is not only highly expressed in various cancers but also identified and verified that it can be used as a potential predictive biomarker for breast cancer through bioinformatics methods." (PMID 38880876, 2024). "However, OTUD6B facilitated breast cancer cell survival by supporting KIFC1 expression." (PMID 40651961, 2025). "With the notable exception of MCF7, the percentage of cells with amplified centrosomes was higher in breast cancer than in normal mammary epithelium cell lines (Fig. EV1A) and correlated with both KIFC1 and OTUD6B levels (Fig. EV1B–D)." (PMID 39789388, 2025). "Interestingly, OTUD6B protein expression was previously associated with breast cancer in a different context, as OTUDB auto-antibodies were identified in the TgMMTV-neu murine model of breast cancer development suggesting their utility for early detection of breast cancer." (PMID 39789388, 2025). "Seven genes were shared between prostate and positive breast cancer responders (TRNT1, NUFIP1, TDG, HSPA8, OTUD6B, RBM12, and DENND3)." (PMID 35520391, 2022). "For instance, increased expression levels of OTUD6B, UCH37, VCPIP1, USP7, and COPS5 have been detected in various breast cancers." (PMID 33070427, 2020). "For example, OTUB1 can inhibit breast cancer growth and invasiveness via nonclassical mechanisms, while OTUD6B can suppress liver cancer metastasis independently of its enzymatic activity." (PMID 39678489, 2024).
lung adenocarcinoma (5 papers, 2022 to 2025). A carcinoma that arises from the lung and is characterized by the presence of malignant glandular epithelial cells. "In lung adenocarcinoma, the deubiquitinated protein OTUD6B promotes tumor progression by stabilizing RIPK1." (PMID 40170095, 2025). "The overexpression of deubiquitinase OTUD6B in lung adenocarcinoma (LUAD) and its adjacent tissues was analyzed by immunohistochemistry and TCGA/GO database." (PMID 38880876, 2024). "OTUD6B depletion also led to a G1/S arrest and reduced proliferation in cancer cells of epithelial origin such as A549 lung adenocarcinoma cells, suggesting a more general role of OTUD6B in promoting cell cycle progression (Fig EV2A–C)." (PMID 36059274, 2022). "Furthermore, OTUD6B facilitated tumor progression in many cancers, including lung adenocarcinoma, laryngeal squamous cell carcinoma, triple-negative breast cancer, and cholangiocarcinoma." (PMID 40651961, 2025). "And OTUD6B promoted lung adenocarcinoma progression by stabilizing RIPK1." (PMID 40651961, 2025).
lung cancer (5 papers, 2022 to 2026). A malignant neoplasm involving the lung. "We found alterations in E-cadherin and N-cadherin, which suggest that the invasive ability of OTUD6B in lung cancer may be related to EMT and may increase the risk of lung cancer metastasis." (PMID 36052059, 2022). "Following the observation of altered expression levels of USP35, USP36, USP37, USP47, USP49, and OTUD6B in response to cisplatin treatment in lung cancer cells, both at the mRNA and protein levels, we sought to explore their significance in lung cancer." (PMID 41399373, 2026). "Multiplex RT-PCR showed distinct mRNA expression profiles of several DUB genes, including USP35, USP36, USP37, USP47, USP49, and OTUD6B in A549 lung cancer cells following exposure to cisplatin." (PMID 41399373, 2026). "In vitro cellular experiments confirmed that the expression level of OTUD6B was significantly higher in lung cancer than in normal tissues, and OTUD6B knockdown inhibited the proliferation, migration, and invasion of lung cancer cells (A549 and Pc9 cells)." (PMID 41050073, 2025). "While we largely demonstrate this effect in MM cells, we also demonstrate activity of the OTUD6B directed nexus in epithelial lung cancer cells, implying a more general functional role of this mechanism beyond MM." (PMID 36059274, 2022). "Results showed that OTUD6B expression was highly expressed in lung cancer compared to normal tissues." (PMID 36052059, 2022). "In addition, lung cancer cell lines with OTUD6B knockdown significantly inhibited proliferation and invasion ability of lung cancer cells." (PMID 36052059, 2022). "Since we observed that OTUD6B has a potential cancer-promoting role in pan-cancers including LUAD, we further performed experiments in lung cancer cell lines to validate its carcinogenic role." (PMID 36052059, 2022). "Substantiating these findings, western blotting analysis confirmed the protein expression levels of USP35, USP36, USP37, USP47, USP49, and OTUD6B in cisplatin-treated lung cancer cells, mirroring the mRNA trends observed in non-treated counterparts except for OTUD6B." (PMID 41399373, 2026).
clear cell renal cell carcinoma (4 papers, 2022 to 2025). "OTUD6B identified as a deubiquitinating enzyme, has been shown to deubiquitinate PVHL, inhibiting tumor progression in clear cell renal cell carcinoma." (PMID 38992675, 2024).
intellectual disability syndrome (4 papers, 2018 to 2022). "Recently researchers disclosed that the OTUD6B biallelic pathogenic variant was associated with epileptic seizures and deformities in 12 individuals from six independent families with intellectual disability syndrome." (PMID 35110537, 2022). "Biallelic mutations in the ovarian tumor domain-containing 6B (OTUD6B) gene, coding for a deubiquitinating enzyme, were recently described to cause an intellectual disability syndrome characterized by seizures and dysmorphic features in six families worldwide." (PMID 30364145, 2018).
multiple myeloma (3 papers, 2022 to 2025). "Inactivation of OTUD6B almost completely eliminates the growth of multiple myeloma (MM) in vivo through cell cycle arrest at the G1/S checkpoint, which is consistent with the associated loss of MYC expression." (PMID 38880876, 2024). "Silencing OTUD6B or LIN28B inhibits multiple myeloma outgrowth in vivo and high OTUD6B expression evolves in patients that progress to symptomatic multiple myeloma and results in an adverse outcome of the disease." (PMID 36059274, 2022). "Here, we screened for DUB vulnerabilities in multiple myeloma, an incurable malignancy with dependency on the ubiquitin proteasome system and identified OTUD6B as an oncogene that drives the G1/S‐transition." (PMID 36059274, 2022). "High OTUD6B expression resulted in an adverse outcome of multiple myeloma." (PMID 40651961, 2025). "In addition, knockout of OTUD6B lead to a significantly enhancement of the anti‐myeloma activity of bortezomib and carfilzomib when using sub‐lethal doses of the drugs." (PMID 36059274, 2022).
triple-negative breast carcinoma (3 papers, 2024 to 2025). An invasive breast carcinoma which is negative for expression of estrogen receptor (ER), progesterone receptor (PR), and human epidermal growth factor receptor 2 (HER2). "In parallel siRNA screens of deubiquitinase enzymes, we identify OTUD6B as a positive regulator of KIFC1 expression that is required for centrosome clustering in triple-negative breast cancer (TNBC) cells." (PMID 39789388, 2025). "In addition, in triple-negative breast cancer, OTUD6B can activate autophagy and DDR inhibition through the OTUD6BAS1/miR-26a-5p/MTDH axis, thereby mediating genomic instability and promoting the development of PTX drug resistance." (PMID 38880876, 2024).
breast invasive carcinoma (2 papers, 2025). "Correlation between the TCGA and CPTAC mass spectrometry data for invasive breast carcinomas confirmed that OTUD6B amplification was associated with increased protein levels." (PMID 39789388, 2025).
colorectal cancer (2 papers, 2025 to 2026). A primary or metastatic malignant neoplasm that affects the colon or rectum. "OTU deubiquitinase 6B (OTUD6B) study in tumors is gradually increasing; however, studies on the role of OTUD6B in colorectal cancer (CRC) are rare." (PMID 40651961, 2025). "When CD8+ T cells were activated, colorectal cancer liver metastasis was suppressed and Otud6b inhibited liver metastasis." (PMID 40651961, 2025). "Our data indicated a pro-tumoral role of OTUD6B, which was inconsistent with the previous survivorship curve, indicating that OTUD6B exerts an antitumor effect on colorectal cancer in patients with CRC." (PMID 40651961, 2025).
developmental delay (2 papers, 2021). "Bi-allelic loss-of-function of OTUD6B causes global developmental delay, feeding difficulties, structural brain abnormalities, and congenital heart disease." (PMID 33335288, 2021). "We noticed that both OTUD6B- and ZMIZ1-related disorders share nonspecific phenotypes of ID, global developmental delay, hypotonia, microcephaly, feeding difficulty, and distal limb anomalies in at least two-thirds of the patients." (PMID 34680978, 2021).
esophageal squamous cell carcinoma (2 papers, 2023 to 2025). Esophageal squamous cell carcinoma (ESCC) is a type of esophageal carcinoma (EC) that can affect any part of the esophagus, but is usually located in the upper or middle third. "And OTUD6B was identified as a potent deubiquitinase of β-TrCP that suppressed esophageal squamous cell carcinoma progression through the OTUD6B-β-TrCP-SNAIL axis." (PMID 40651961, 2025). "All-trans retinoic acid (ATRA) enhanced OTUD6B protein level, hence inhibiting esophageal squamous cell carcinoma (ESCC) progression." (PMID 40651961, 2025). "This work identifies OTUD6B as a potent deubiquitinase of β‐TrCP that suppresses esophageal squamous cell carcinoma (ESCC) progression through the OTUD6B‐β‐TrCP‐SNAIL axis." (PMID 37038094, 2023).
Intellectual disability (2 papers, 2018 to 2021). "In 2017, Autosomal recessive mutations of OTUD6B were first described to cause intellectual disability associated with seizure, dysmorphic features, and congenital malformations, including distal limb abnormalities." (PMID 34680978, 2021). "Here, we report the identification of biallelic mutations in OTUD6B in a patient with mild intellectual disability associated with seizures and dysmorphic features." (PMID 30364145, 2018). "The OTUD6B and ZMIZ1 genes were recently identified as causes of syndromic intellectual disability (ID) with shared phenotypes of facial dysmorphism, distal limb anomalies, and seizure disorders." (PMID 34680978, 2021).
liver cancer (2 papers, 2020 to 2024). An epithelial or non-epithelial malignant neoplasm that arises from the liver. "Furthermore, OTUD6B is identified as a direct target of HIF‐1α and the negative feedback loop between OTUD6B and HIF‐1α regulates liver cancer metastasis under hypoxia." (PMID 32328410, 2020).
non-small cell lung carcinoma (2 papers, 2022 to 2024). A group of at least three distinct histological types of lung cancer, including non-small cell squamous cell carcinoma, adenocarcinoma, and large cell carcinoma. "Two OTUD6B splice isoforms recognize different substrates and have completely opposite effects on non-small cell lung cancer cell proliferation." (PMID 38685067, 2024). "OTUD6B has been reported to regulate cell cycle in non small cell lung cancer cells." (PMID 35110537, 2022).
cervical cancer (1 paper, 2025). A primary or metastatic malignant neoplasm involving the cervix. "In contrast, other OTU members exert anti-cancer effects in specific cancers, such as YOD1 in HNSCC and cervical cancer; OTUD1 and OTUD6B in clear cell renal cell carcinoma (ccRCC); TNFAIP3 in nasopharyngeal carcinoma (NPC)." (PMID 40469292, 2025).
colon adenocarcinoma (1 paper, 2025). "OTUD6B mRNA level was significantly upregulated in colon adenocarcinoma (COAD) and rectum adenocarcinoma (READ) samples compared to normal tissues, as indicated by data from the TCGA database accessed through the UALCAN database." (PMID 40651961, 2025).
esophageal carcinoma (1 paper, 2023). A primary or metastatic malignant neoplasm involving the esophagus. "Knockout of OTUD6B significantly promoted the development of esophageal carcinoma in the 4NQO‐induced model." (PMID 37038094, 2023).
laryngeal carcinoma (1 paper, 2019). Carcinoma that arises from the laryngeal epithelium. "Assessment of these genes in clinical sub-cohorts of TCGA indicated that early stage tongue (MTFR1, C8ORF33, OTUD6B) and laryngeal cancers (TWISTNB, KLHL13 and UBE2Q1) were defined by distinct prognosticators." (PMID 31310629, 2019).
lymph node metastasis (1 paper, 2023). "A lower OTUD6B level was observed in patients with lymph node metastasis compared with those without metastasis." (PMID 37038094, 2023).
ovarian tumor (1 paper, 2025). "OTU deubiquitinase 6B (OTUD6B) belongs to the ovarian tumor family deubiquitinases." (PMID 40651961, 2025).
prostate carcinoma (1 paper, 2022). A carcinoma that arises from epithelial cells of the prostate gland. "Intriguingly, we found that unlike OTUD6B, OTUD6A was specifically and highly amplified in prostate cancer." (PMID 35233061, 2022).
seizure disorders (1 paper, 2021). "The patient’s phenotypes better match OTUD6B-linked characteristics, namely, epilepsy, prominent nasal bridge, arched eyebrows, and broad thumb/polydactyly." (PMID 34680978, 2021). "However, some features were relatively prevalent and more specific to those of OTUD6B-linked ID, including substantial epilepsy, characteristic facial dysmorphisms, arched eyebrows/long palpebral fissures, prominent nasal bridge; broad thumb with/without polydactyly (postaxial)." (PMID 34680978, 2021).